RETN (resistin)
Diseases named in the same sentence as RETN in open-access papers (continued):
Sharing a sentence is not in itself a finding about the gene and the disease.
Obesity (continued). "In mice, administration of resistin impairs glucose tolerance and insulin action, implying that elevated levels of resistin may link obesity to diabetes." (PMID 27148161, 2016). "Resistin is up-regulated while adiponectin is down-regulated in diabetes and obesity." (PMID 25960181, 2015). "Data correlating circulating resistin with human obesity and insulin resistance are contradictory." (PMID 25129652, 2015). "However, it is generally accepted that raised levels of resistin can be found in these animal models of obesity and diabetes." (PMID 26097512, 2015). "A close relationship between obesity and cancer has been suggested, and resistin, which is a specific inflammatory cytokine produced by the adipose tissue, may contribute to supporting the oxidative stress process which regulates tumor metabolic homeostasis." (PMID 25691058, 2015). "These interactions may be important in conditions in which leptin and resistin are elevated, such as in obesity." (PMID 26617526, 2015). "In contrast to rodents, the expression of resistin in human adipocytes is low, and the main source of resistin in humans is macrophages, and in obesity, macrophages that have infiltrated into visceral white adipose tissue are the predominant source of resistin." (PMID 26617526, 2015). "Resistin is thought to impair glucose tolerance in pregnancy and several studies have shown a positive correlation between obesity and insulin resistance in pregnancy and elevated plasma resistin, but others have not found this association." (PMID 26110385, 2015). "Increasing evidence from clinical studies suggests that resistin is implicated in various human pathologies, including MetS, type 2 diabetes, cardiovascular disease [CVD], and obesity-related subclinical inflammation, but the role of resistin in the development of NAFLD is controversial." (PMID 25922835, 2015). "It has been hypothesized that dysregulated production of adipocytokines (PAI-1, leptin, resistin, visfatin, adiponectin) and cytokines (TNF-α and IL-6) from accumulated fat participates in the pathogenesis of obesity-associated MS." (PMID 25548896, 2014). "In addition, resistin is suggested to be an important link between obesity and the development of gastric cancer." (PMID 24929539, 2014). "Resistin-induced SDF-1 upregulation by activation of TLR4, p38 MARK and NF-κB may explain a new role of resistin in the link of obesity and gastric cancer." (PMID 24929539, 2014). "While studies have shown that plasma levels of resistin and visfatin increase with obesity, the association between PCOS and these markers has not been described well." (PMID 25237319, 2014). "In obesity, there is an increased production of free fatty acids, angiotensinogen, leptin, resistin and inflammatory mediators that might be involved in mechanisms of obesity-associated microvascular dysfunction." (PMID 25036223, 2014). "Moreover, human monocyte expression of NAMPT is more closely related to parameters of glycemia, whereas resistin correlates more strongly with obesity." (PMID 24968098, 2014). "Resistin concentrations increase with obesity, therefore concentrations of breast milk resistin might be expected to increase with maternal BMI." (PMID 25536196, 2014). "Its presence at such high expression levels suggests that resistin may play an important role in AA BRCa because of the strong link between obesity and cancer mortality." (PMID 24324792, 2013). "Scientists have suggested that resistin is a hormone that links obesity to diabetes." (PMID 23634778, 2013). "Moreover, in addition to NAMPT, the levels of other adipokines, such as leptin, resistin, and adiponectin, are altered in obesity and periodontal inflammation." (PMID 24288440, 2013). "The serum concentration of resistin in humans ranges from 7 to 22 ng/mL; however, in patients with type 1 or 2 diabetes, obesity, and/or inflammatory conditions, plasma resistin levels may exceed 40 ng/mL." (PMID 24386395, 2013).
Obesity (continued). "Deletion of the resistin gene reduces the impact of obesity on glucose homeostasis." (PMID 23497617, 2013). "An elevated level of circulating resistin was detected in obesity and diabetes." (PMID 23634778, 2013). "TNF-α and resistin, adipocytokines, are known to be elevated in obesity." (PMID 24049664, 2013). "The adipokine, resistin, was proposed originally to be a link between obesity and type 2 diabetes." (PMID 23484124, 2013). "Further studies should explore if resistin may be one of the factors explaining the relation between obesity and AD." (PMID 23476106, 2013). "Adipose tissue, which is accumulated in obesity, is a key endocrine organ that produces multiple biologically active molecules, including leptin, adiponectin, resistin, that affect inflammation, and subsequent deregulation of cell function in renal glomeruli that leads to pathological changes." (PMID 22567283, 2012). "In obesity, the release of adipokines such as leptin, resistin, and adiponectin can be altered." (PMID 22645452, 2012). "In rodents, the circulating levels of resistin increased in obesity." (PMID 22110480, 2012). "Resistin is associated with elevated CRP and white blood cells, suggesting that the role of resistin may be a component of obesity-related inflammation." (PMID 22567283, 2012). "We hypothesize that these factors (FFAs, TNF-α, and resistin) and drug (rosiglitazone) may have a potential regulatory mechanism in obesity through the regulation of LYRM1 mRNA expression, thereby affecting insulin sensitivity." (PMID 22110480, 2012). "Given the obesity-insulin resistance-inflammation link and convergence of adipocyte and macrophage function, resistin may provide unique insight into links between obesity, inflammation, and metabolic syndrome risk in humans." (PMID 22969799, 2012). "In addition, application of anti-resistin antibodies improves blood glucose and insulin efficacy in murine models of diet-induced obesity." (PMID 22545721, 2012). "Measurement of resistin in saliva is a simple, noninvasive and may be an acceptable alternative to blood sampling for evaluatinginflammation/obesity/insulin resistance state." (PMID 22969799, 2012). "Serum resistin levels increase with obesity in mice, rats, and humans." (PMID 22046513, 2011). "The peptide hormone resistin, also called FIZZ3, is an adipocyte-derived secretory factor which was first identified as a novel transcript produced exclusively by adipocytes and has been shown to play a significant role in obesity-induced insulin resistance." (PMID 21760816, 2011). "Moreover, obesity affects the synthesis of adipokines (e.g. leptin, adiponectin and resistin), which operate in a variety of metabolic and immunologic activities, for instance regulating food intake, insulin resistance and inflammation." (PMID 20646281, 2010). "It has been demonstrated that resistin impairs glucose tolerance and antagonizes insulin action, indicating that resistin may be an important cytokine linking obesity to diabetes." (PMID 21113299, 2010). "Among the biomarkers that we measured, RBP4 and resistin have previously been shown to be necessary and sufficient to induce insulin resistance and genetic disruption or impaired leptin signaling has been shown to lead to obesity and insulin resistance." (PMID 20633301, 2010). "Therefore, RBP4 and resistin levels appear to better predict obesity and insulin resistance than leptin in our model." (PMID 20633301, 2010). "Recombinant resistin protein was found to impair insulin action in normal mice and cultured adipocytes, and immunoneutralization of resistin improved insulin action in mice with diet-induced obesity." (PMID 19649297, 2009). "A variety of adipocyte-derived biologically active molecules have been identified, including leptin, resistin, TNF-α, and IL-6, that may contribute to obesity-linked metabolic abnormalities." (PMID 19254366, 2009).
Obesity (continued). "Animal studies show that resistin is produced mainly in white adipose tissue and may be the linkage between obesity and insulin resistance." (PMID 18234104, 2008). "The amount of resistin is high in mice that have obesity and insulin resistance." (PMID 21876654, 2008). "The putative role of resistinin obesity-induced insulin resistance was confirmed by studies, in rodents,demonstrating that administration of recombinant resistin impairs hepaticinsulin sensitivity and glucose metabolism, while possibly playing a rolein maintaining fasting blood glucose levels." (PMID 19125180, 2008). "To date, there has been considerable controversy surrounding the physiological relevance of resistin: the associations with insulin resistance and obesity, reported in mice, have not been conclusively demonstrated in humans." (PMID 17479165, 2007). "Resistin, a recently described adipokine belonging to the cysteine-rich secretory protein family, was originally described as an adipocyte-derived polypeptide that links obesity and insulin resistance in mice." (PMID 17479165, 2007). "Our data, for the first time, demonstrate resistin's role in adipose tissue as a potential autocrine mediator of insulin resistance and inflammation that accompanies enlarging fat cell size and progressive obesity." (PMID 16854242, 2006). "Therefore resistin has also been proposed as an adipocyte-secreted factor thought to link obesity and T2DM, although subsequent rodent studies have reported contrasting findings to this." (PMID 15998471, 2005). "Inflammation is a hyperresistinemic state in humans, and cytokine induction of resistin may contribute to insulin resistance in endotoxemia, obesity, and other inflammatory states." (PMID 15578112, 2004). "Researchers are now studying what role—if any—resistin might have in humans with obesity and diabetes and are studying the similarities in the ways in which the body reacts to obesity and inflammation." (PMID 15578112, 2004). "However, only IL-6, leptin, adiponectin, and resistin serum levels were found to be significantly associated with diabetes without obesity, after adjusting for age." (PMID 40095937, 2025). "In obesity, chronic low-grade inflammation and elevated basal expression of Toll-like receptors and NF-κB signaling components may prime monocytes and macrophages for a stronger proinflammatory and microbicidal response to resistin stimulation." (PMID 41301907, 2025). "Indeed, the influence of resistin on metabolic health and obesity might vary among Mexican-Americans compared to other groups." (PMID 40362681, 2025). "Given that obesity influences both metabolic and immune functions, and considering the intricate immunological and nutritional relationship between mother and child during pregnancy and lactation, resistin may play a key role in mediating these effects." (PMID 41301907, 2025). "However, only IL-6, leptin, adiponectin, and resistin serum levels were found to be significantly associated with diabetes without obesity, even after adjusting for sex (Model 2) or age (Model 3)." (PMID 40095937, 2025). "Such analyses could provide valuable information regarding the role of resistin as a potential mediator of the mechanisms linking obesity and depression and could clarify whether a synergy between excess weight and resistin influences the risk of developing mood disorders." (PMID 40507778, 2025). "Notably, although resistin levels are significantly elevated in T2DM, the relationship between resistin and insulin resistance, obesity or hyperlipidemia remains unclear." (PMID 39812542, 2025). "Similarly, resistin, a member of the resistin-like molecule family (RELMs), is elevated in obesity." (PMID 40558305, 2025). "However, as adipose tissue (AT) is infiltrated by macrophages in obesity, resistin might remain a relevant factor in obesity-related metabolic health." (PMID 40362681, 2025). "Moreover, the level of resistin is elevated in obesity and the patient with T2DM." (PMID 39812542, 2025).
Obesity (continued). "However, over the last years, the study of resistin gained increased popularity since it was proved that there is a considerable relationship between high levels of resistin and obesity as well as obesity-induced diseases, including diabetes, cardiovascular disorders, and cancer." (PMID 39184804, 2024). "Furthermore, the regulation of resistin via the CB1R might be a good therapeutic strategy for cardiovascular diseases by controlling obesity-related inflammation and insulin resistance." (PMID 39050819, 2024). "Moreover, emerging studies suggest that adipokines, such as resistin, apelin, and chemerin, which are overexpressed in obesity, may also possess oncogenic functions." (PMID 38255203, 2024). "Obesity is a chronic inflammatory disorder, associated with adipocyte hypertrophy and secretion of pro-inflammatory cytokines, such as interleukin (IL)-6, IL-1, IL-8, and tumor necrosis factor (TNF)-α, as well as adipokines such as leptin, adipsin, resistin, and visfatin by adipose tissue." (PMID 38864906, 2024). "HCV patients have reduced levels of adiponectin and leptin, and increased levels of resistin, ghrelin and vizfatin, contributing to inflammation, insulin resistance, lipid disorders and atherosclerosis and consequently to the development of hypertension and obesity." (PMID 39457712, 2024). "On the other hand, resistin, an adipokine produced in the vascular stroma of human white adipose tissue, is known for its role in promoting insulin resistance and inflammation with associated elevated concentrations of type 2 diabetes mellitus (DM2) and obesity." (PMID 38399430, 2024). "Therefore, apelin-12, vaspin and resistin may be used as biomarkers in children and adolescents with overweight and obesity." (PMID 39519480, 2024). "Gene editing or specific inhibitors could be applied to our system to define the effects of adipokines such as adiponectin, leptin, resistin and omentin or metabolic and inflammatory pathways that impact hepatic insulin response in the setting of obesity and WAT inflammation." (PMID 39266553, 2024). "Similarly, only a single study investigated the effectiveness of carnosine supplementation on other adipokines, including serum leptin, resistin, and adipsin, indicating that carnosine intake reduced serum leptin and resistin levels in adults with overweight or obesity." (PMID 38086332, 2024). "Consequently, the suppression of leptin and resistin expression may be an alternative means of combating obesity." (PMID 37371984, 2023). "In agreement, Grewal and Buechler demonstrated that adipokines, mainly leptin, resistin and galectin-3, are closely involved in peripheral monocytes and neutrophil responses, which contributes to complications during the course of COVID-19 in patients with obesity." (PMID 37626613, 2023). "However, these resistin-based predictions were unrelated to obesity and metabolic syndrome." (PMID 37238973, 2023). "The effect of resistin on the vasoactive endothelial function is of interest—resistin enhances the endothelin-1 expression in endothelial cells, which may be one of the elements responsible for an increased blood pressure in obesity." (PMID 36674022, 2023). "In obesity, not only the nutritional status of the individual changes, but also concentrations of messenger molecules, such as leptin, adiponectin, resistin, visfatin, and others, which may directly affect Th2 cell function or indirectly inhibit Th2 cells by promoting Th1/Th17-biased inflammation." (PMID 35844529, 2022). "However, some of its peptides are unclear, for instance, resistin, an antagonist polypeptide of insulin action that may play a role in obesity." (PMID 36466401, 2022). "In addition, it has been shown that resistin levels are positively correlated with insulin resistance in people with hyperresistinemia, in contrast to people with normal levels of circulating resistin in obesity and T2DM." (PMID 36499312, 2022).
Obesity (continued). "However, the identification of a specific receptor for human resistin could provide a better understanding of its molecular roles in human obesity and metabolic diseases." (PMID 35909571, 2022). "However, in contrast, pathogenic mechanism of obesity-related inflammatory IVDD-associated with other adipokines such as resistin has not been widely investigated." (PMID 35624126, 2022). "Consequently, suppression of leptin and resistin expressions is an alternative against obesity." (PMID 35806278, 2022). "As for obesity, a different impact of several risk factors in micro- and macrovascular complications has been reported in T2DM men and women, and gender-related differences in the association of plasma levels of resistin with anthropometric parameters were also observed." (PMID 34496965, 2021). "Changes in the production of adipokines such as leptin, resistin, lipocalin 2, tumor necrosis factor-α, chemerin, retinol binding protein 4, and interleukin-6 have been reported in obese individuals, and this can lead to the development of obesity-related metabolic diseases." (PMID 33498329, 2021). "However, the role of resistin in obesity and insulin dysregulation is highly controversial." (PMID 35011183, 2021). "In those women, the indicative of obesity was BMI and waist circumference (WC) characteristics of visceral obesity, in addition to positive correlation between the concentration of leptin and WC, between the levels of resistin and insulin and the levels of resistin and HOMA." (PMID 33520042, 2021). "Thus, resistin could be the metabolic link between obesity and insulin resistance, since resistin levels are high in inflammatory states such as in obese subjects promoting then insulin resistance." (PMID 33686181, 2021). "Obesity is a very complex abnormal state, accompanied by various physiological and molecular alterations, which involves the complicated roles of adipokines (leptin, adiponectin, resistin, visfatin, and SFRP5), insulin, IGF, sex hormone, and chronic inflammation." (PMID 34350120, 2021). "Whether the expression of these genes was involved in the resistin expression needs further investigation because the resistin expression in obesity has been in controversy, and in vitro treatment with resistin leads to a reduction in the rate of cellular fatty acid oxidation." (PMID 32586265, 2020). "In addition, children with overweight or obesity tend to have lower concentrations of IL-10 and IGFBP-1, which can predispose them to low grade inflammation often reflected in higher circulating levels of CRP and resistin." (PMID 33266497, 2020). "Thus, resistin may in-part explain independent relations between obesity and heart failure and circulating concentrations of resistin may act as potential biomarker for the development of heart failure in obesity." (PMID 32000666, 2020). "The excess fat mass that characterizes obesity is produced by an expansion of adipose tissue not only as an inert energy reservoir, but also as an endocrine organ producing various adipokines such as leptin, adiponectin, adipsin, resistin, and approximately 50 biologically active proteins." (PMID 32947606, 2020). "Therefore, we supposed that alteration of gut microbiota might affect the transcriptional expression of adiponectin and resistin through epigenetic regulation in obesity." (PMID 32586265, 2020). "In addition, leptin together with resistin could also function as a pro-inflammatory molecule in the presence of obesity, while adiponectin and ghrelin have anti-inflammatory properties." (PMID 30715588, 2019). "Indeed, plasma human resistin seems to be correlated wth IR as a consequence of obesity itself rather than as an independent causative factor." (PMID 31505789, 2019). "Indeed, resistin is considered as a potential link between obesity and insulin resistance." (PMID 30845245, 2019).